NANOS2 (nanos C2HC-type zinc finger 2)
Description:
Plays a key role in the sexual differentiation of germ cells by promoting the male fate but suppressing the female fate. Represses the female fate pathways by suppressing meiosis, which in turn results in the promotion of the male fate. Maintains the suppression of meiosis by preventing STRA8 expression, which is required for premeiotic DNA replication, after CYP26B1 is decreased. Regulates the localization of the CCR4-NOT deadenylation complex to P-bodies and plays a role in recruiting the complex to trigger the degradation of mRNAs involved in meiosis. Required for the maintenance of the spermatogonial stem cell population. Not essential for the assembly of P-bodies but is required for the maintenance of their normal state (By similarity).
Synonyms: NOS-2; NOS2; ZC2HC12B
Tractability: No criterion of Open Targets' tractability assessment is met for any kind of drug.
Gene: Protein-coding gene on chromosome 19 (45,913,214 to 45,914,778, reverse strand). Ensembl gene ENSG00000188425.
Subcellular location: Cytoplasm; Cytoplasm, P-body; Cytoplasm, perinuclear region
Gene Ontology:
Molecular function: enzyme activator activity; protein binding; mRNA binding; RNA binding; zinc ion binding
Biological process: mRNA destabilization; negative regulation of translation; germ-line stem cell population maintenance; mRNA catabolic process; negative regulation of meiotic nuclear division; oogenesis; spermatogenesis
Cellular component: cytoplasm; nucleus; perinuclear region of cytoplasm; P-body
Genetic constraint (gnomAD): Loss-of-function variants: 3 observed, 6.77 expected, observed/expected ratio (o/e) 0.44, 90% interval 0.2 to 1.14. That is too few expected variants to judge how well the gene tolerates losing a copy. Missense variants: 177 observed, 201.29 expected, observed/expected ratio (o/e) 0.88, 90% interval 0.78 to 1. Synonymous variants: 86 observed, 91.63 expected, observed/expected ratio (o/e) 0.94, 90% interval 0.79 to 1.12.
Homologues: Orthologues: chimpanzee NANOS2 (100% identical), macaque NANOS2 (97% identical), dog NANOS2 (84% identical), rabbit NANOS2 (84% identical), pig NANOS2 (83% identical), guinea pig NANOS2 (75% identical), mouse Nanos2 (75% identical), rat Nanos2 (74% identical), Drosophila melanogaster nanos (31% identical), zebrafish nanos2 (30% identical), Caenorhabditis elegans nos-1 (28% identical), Caenorhabditis elegans nos-2 (22% identical). Paralogues in human: NANOS3 (43% identical), NANOS1 (33% identical).
Diseases named in the same sentence as NANOS2 in open-access papers:
NANOS2 is named in the same sentence as 8 diseases in open-access papers, as found by Europe PMC text mining. Sharing a sentence is not in itself a finding about the gene and the disease. The quoted sentences say what the papers report.
Infertility (4 papers, 2018 to 2025). "Knockout of Nanos2 causes the apoptosis of male PGCs, eventually leading to the loss of testicular germ cells and infertility of male mice." (PMID 30322389, 2018). "Therefore, a study was conducted to investigate the NANOS2 gene for variants in a group of 214 infertile male patients with non-obstructive azoospermia or oligozoospermia from the Polish cohort, alongside 400 fertile males from the same population." (PMID 41107697, 2025). "While disruption of NANOS2 and NANOS3 in mice causes infertility, NANOS1, although expressed in germ cells, does not seem to play a significant role in reproduction or other processes in mouse physiology." (PMID 41107697, 2025).
male infertility (4 papers, 2010 to 2025). The inability of the male to effect fertilization of an ovum after a specified period of unprotected intercourse. "In the future, it will be interesting to see if mutations within NANOS2 consensus sites in target genes are associated with male infertility in mouse models or in humans." (PMID 34278268, 2021). "Similar to the mouse orthologue, human NANOS2 was shown to be expressed specifically in male germ cells, indicating a potential association between NANOS2 mutations and male infertility." (PMID 32344590, 2020).
cryptorchidism (1 paper, 2013). The failure of one or both testes of a male fetus to descend from the abdomen into the scrotum during the late part of pregnancy. "Another marker affected by cryptorchidism is NANOS2, an RNA binding protein." (PMID 24098584, 2013).
embryonal carcinoma (1 paper, 2022). A non-seminomatous malignant germ cell tumor characterized by the presence of large germ cells with abundant cytoplasm resembling epithelial cells, geographic necrosis, high mitotic activity, and pseudoglandular and pseudopapillary structures formation. "Single-cell RNAseq studies on NANOS2 deficient germ cells (collected on D15.5) and embryonal carcinoma cells showed that both develop a transcriptional profile enriched for MYC and NODAL signaling and primed pluripotency." (PMID 35676718, 2022). "Also, that embryonal carcinoma arises from NANOS2 negative germ cells." (PMID 35676718, 2022).
teratoma (1 paper, 2020). A non-seminomatous germ cell tumor characterized by the presence of various tissues which correspond to the different germinal layers (endoderm, mesoderm, and ectoderm). "However, the following are unclear: (a) whether DND1 works with NANOS2 or NANOS3 to regulate teratoma incidence, and (b) whether Ter simply causes Dnd1 loss or produces a short mutant DND1 protein." (PMID 32339196, 2020). "In addition to these genetic interactions, given that both NANOS2 and NANOS3 associate with DND1, it is highly plausible that both DND1-NANOS2 and DND1-NANOS3 complexes regulate teratoma incidence in male embryonic germ cells." (PMID 32339196, 2020).
testicular teratoma (1 paper, 2020). "Therefore, the regulatory mechanisms of the DND1-NANOS3 complex in the case of testicular teratoma incidence are still unknown and may differ from those of NANOS2." (PMID 32339196, 2020). "We have previously shown that both NANOS2 and NANOS3 interact with DND1 and that these complexes are essential for germ cell development, leading us to speculate that both NANOS2 and NANOS3 play a vital role with DND1 even in the regulation of testicular teratoma incidence." (PMID 32339196, 2020). "We have previously shown that DND1 functions with NANOS2 or NANOS3 in both male embryonic germ cells and adult spermatogonia, which raises the question of whether DND1 also acts as a partner of NANOS family proteins to regulate the incidence of testicular teratoma." (PMID 32339196, 2020).
testis cancer (1 paper, 2022). "This indicates that a lack of NANOS2 protein increases the susceptibility of testis cancer." (PMID 36012673, 2022).
NANOS2 also shares sentences with these, for which no sentence is quoted: cancer (2 papers).